IL11 (interleukin 11)
Diseases named in the same sentence as IL11 in open-access papers (continued):
Sharing a sentence is not in itself a finding about the gene and the disease.
cancer (continued). "The second, F6: inflammatory myofibroblasts (IL11+MMP1+CXCL8+IL7R+), characterizes early human skin wounds, inflammatory diseases with scarring risk and cancer." (PMID 40993240, 2025). "For example, studies show that CAFs secrete IL-6 and IL-11 to activate STAT3 signaling in cancer cells, enhancing survival and resistance to apoptosis." (PMID 40718440, 2025). "High IL‐11 expression was clearly related to a poorer OS (N = 527, p = .040, HR 1.387 [1.014–1.899]) in LUAD patients, suggesting a role for IL‐11 in cancer progression." (PMID 40673604, 2025). "A few preclinical studies have explored therapeutic targeting of IL-11 or its signaling pathways in different types of cancers." (PMID 41154660, 2025). "Interleukin‐11 (IL‐11) has emerged as a significant player in tumourigenesis, with implications across various cancer types." (PMID 40673604, 2025). "Deletion of the IL-11 gene or its receptor prolongs lifespan in aging mice and an antibody to IL-11 delays the onset of age-related conditions such as cancer and frailty." (PMID 40554265, 2025). "For instance, n-3 PUFAs have been shown to suppress levels of IL-6 and TNF-α in cancer patients, as well as reduce IL-17A-mediated inflammation and IL-11 expression in hepatocytes during acetaminophen-induced hepatotoxicity." (PMID 40704145, 2025). "TNF-α, particularly, has demonstrated the ability to stimulate keratinocyte proliferation, potentially contributing to cSCC development, while IL-6 and IL-11 can enhance cancer cell survival and migration, thereby bolstering cSCC growth." (PMID 40013270, 2024). "As elevated serum IL-6, IL-8, and IL-11 levels correlate to worse survival in cancer patients, we sought to measure IL-8 in both the serum and plasma samples in the NSCLC patients compared against normal volunteers." (PMID 39329890, 2024). "RUNX2-suppressor of mothers against decapentaplegic (Smad) and Runx2-c-Jun interact to increase IL-11 gene expression, which promotes cancer-induced osteolytic bone disease." (PMID 38745115, 2024). "Cancer cells can be characterized by overexpression of certain cytokines groups, e.g., IL-6 or IL-11." (PMID 38258051, 2023). "Although it has been revealed that IL11 was closely related to the initiation and progression of cancer, there are few studies specify its regulatory mechanism." (PMID 37365574, 2023). "We next explored the relation between stromal TGF-beta pathway activation and IL11 activity in epithelial CRC cells during cancer progression." (PMID 36765091, 2023). "In the earlier literature IL11 levels were found to be elevated in the synovial fluid of patients with OA and IL11 is thought important for bone resorption in cancer metastasis." (PMID 38054591, 2023). "IL-11 regulates inflammation and fibrosis, hematopoiesis, adipogenesis, fertility, and cancer development." (PMID 38352248, 2023). "The impact of IL11 in healthspan is intriguing, but findings need to be extended to other age-related pathologies such as cancers, thymic dysfunction, brain disorders and to lifespan." (PMID 38054591, 2023). "In cancers, IL11 is thought to have both cell autonomous effects in cancer cells and fibroblasts as well as paracrine cross-talk between cells." (PMID 38054591, 2023). "Many genes that were significantly upregulated in the RDEB inflammatory fibroblast subset, e.g., Il11, Lif, Vegf, Saa3, Tnc, and C3, are also the signature genes of iCAFs identified in many cancers." (PMID 37809094, 2023). "Inhibition of IL11, by a variety of means, is associated with reduced cancer initiation, progression and metastasis and IL11 is being explored as a therapeutic target in combination with immunotherapy for some human cancers by Mabwell Therapeutics (below)." (PMID 38054591, 2023). "In this review, we aimed at updating and summarizing the role of IL-11 in bone metabolism and homeostasis, including bone development, formation and resorption, and cancer bone metastasis." (PMID 37199584, 2023).
cancer (continued). "TIMER2.0 website analysis indicated that IL11 was negatively correlated with CD8+ T cell infiltration broadly in several cancers, especially in CRC." (PMID 37365574, 2023). "In breast cancer, gastric cancer, colon cancer, and other malignant tumors, IL-11 promotes and accelerates angiogenesis in cancerous tissues." (PMID 37304948, 2023). "IL-11/IL-11R signaling enhances osteoblast differentiation and bone formation and mitigates osteoclast-induced bone resorption and cancer bone metastasis." (PMID 37199584, 2023). "As the roles for IL‐11 and its receptors become increasingly clear in diseases such as fibrosis and cancer, methods of inhibiting this signaling axis are of great interest." (PMID 38023717, 2023). "The role of IL11 in various forms of cancer, notably gastric, breast, lung and colonic, has been the subject of many reviews and is mentioned briefly here." (PMID 38054591, 2023). "Different cytokine-related pathways were upregulated in the stroma during the progression from normal mucosa to carcinoma, including interferon γ, interleukin (IL)-11, IL-10, IL-6, IL-9, IL1R and IL-18 signalling pathways." (PMID 36442992, 2023). "IL33 is an alarmin important for immunity, inflammation, epithelial barrier function and cancer, and it was the most upregulated signaling factor following IL11 exposure." (PMID 36012165, 2022). "Consistent with this, our study confirmed the upregulation of IL‐6, LIF and IL‐11 in iCAF after the activation of PSCs by CM from cancer cells." (PMID 36282889, 2022). "Other cancer-related interaction partners of S100P are interleukin-11 and interferon-β, and their binding can modulate local inflammation processes and the host immune response." (PMID 35597866, 2022). "IL-11 can increase the oncogenic properties of cells, including, cancer cell proliferation and survival." (PMID 35844493, 2022). "Their ability to secrete interleukin-11 (IL-11) for instance, increases initiation of metastasis in cancer cells." (PMID 35815339, 2022). "A statistically significant difference in patient survival was observed between high and low tissue IL11 mRNA expression among LUAD and SCC patients in the TCGA Pan-Cancer Atlas dataset and high IL11 expression was associated with poorer survival." (PMID 35883698, 2022). "Another fibroblast-derived immune mediator that plays a role in cancer development is the IL-6 family member IL-11." (PMID 36591258, 2022). "Due to its pro-tumorigenic activities, IL-11 signalling inhibition appears as a new strategy to be used in cancer therapy." (PMID 34201209, 2021). "Characterisation of a range of cancer cell lines, including a BC model, found that IL11 and IL11R expression was induced by the development of hypoxia." (PMID 34834425, 2021). "IL-11 appears as a multifunctional cytokine with known roles on cancer (clearly pro-tumorigenic and pro-metastatic)." (PMID 34201209, 2021). "Of note, IL-11 is expressed by cells of the osteoblast lineage; therefore, cancer cells, other than producing IL-11, respond to this signal once they arrive in the bone marrow." (PMID 34201209, 2021). "Targeting human IL-11, or its signalling, in different types of cancer has been reported in few preclinical models." (PMID 34201209, 2021). "The role of IL-11 in cancer has been the subject of extensive studies in view of the emerging evidence indicating IL-11 as a signalling mediator in cancer cells in defining worst outcomes." (PMID 34201209, 2021). "Studies employing animal models have provided significant insights on the importance of IL-11 for cancer progression and it has been demonstrated that IL-11 drives metastasis in mouse models." (PMID 34201209, 2021). "By neutralizing IL-11 in the conditioned medium the authors showed that IL-11 was indeed the predominant cancer-derived factor that affects osteoclast precursor development and/or survival." (PMID 33809315, 2021).
cancer (continued). "Osteolytic resorption further releases active factors, including TGF-β, that support cancer cell survival and growth, which in turn secrete more osteolytic factors such as PTHrP, IL-11, VEGF, and MMPs15–19." (PMID 33731701, 2021). "This review focuses on IL-11, a pleiotropic cytokine that, in addition to its well-known effects on several tissues, also mediates certain signals in cancer cells." (PMID 34201209, 2021). "Interleukin‐11 (IL-11) has been reported to be upregulated in various types of human cancer and correlate with clinical stage and poor survival." (PMID 34149927, 2021). "Both, medium conditioned by cancer cells and IL-11 supported the development and survival of osteoclast progenitor cells in vitro." (PMID 33809315, 2021). "We focused on genes with over twofold greater expression in IL-11+ fibroblasts compared with IL-11− fibroblasts, and extracted 22 genes matching our criteria from the human cancer databases (GSE33133 and GSE35602)." (PMID 33863879, 2021). "In line with the typical signalling of cytokines in the IL6-like family, STAT3 is a central orchestrator of most of the known effects of IL11 in cancer, including promotion of cell growth and survival." (PMID 34834425, 2021). "The involvement of IL-11 in different stages of cancer development and progression has spurred many studies aimed at counteracting IL-11 itself or its signalling with different molecular approaches." (PMID 34201209, 2021). "CAFs produce several cytokines such as IL-6, IL-11, and IL-22 and create a favorable environment for cancer." (PMID 34063828, 2021). "Chemokines and cytokines affect different stages of the metastatic process, and in bone metastases, interleukin (IL) -6, IL-8, IL-1β, and IL-11 participate in the interaction between cancer cells and bone cells." (PMID 34201209, 2021). "FACS analysis revealed that IL-11 significantly increased the proportion of CD133+ ALDH1A1+ cells, suggesting a role for IL-11 in the regulation of cancer stem cells." (PMID 32686598, 2020). "Another example is IL-11, a pro-metastatic factor that can be successfully targeted by IL-11 signaling antagonist to reduce cancer progression." (PMID 33553157, 2020). "IL-11 or IL-6 inhibitors displayed potent anti-cancer activity in pre-clinical models of cancer of distinct origins." (PMID 33553157, 2020). "For example, colonization of fecal microbiota transplantation (FMT) from SPF mice or intragastric administration of Bifidobacterium into GF mice or ABX mice reduces cancer progression, along with the release of IL-11." (PMID 32686598, 2020). "Alternatively, treatment of lung adenocarcinoma with cisplatin enhances IL-11 secretion by CAFs, which in turn promotes resistance of cancer cells to CT through the STAT-3 signaling pathway." (PMID 33553157, 2020). "IL-11 transcription is largely dependent upon transcription factors such as AP-1, SMADs, and p65NF-κB in cancer cells." (PMID 31299894, 2019). "More cytokines are generated during the inflammation course in cancer, such as IL-6 and IL-11, and highly upregulated in many cancers." (PMID 31781655, 2019). "Autocrine IL-11 also mediates tumorigenicity in hypoxic human cancer cells by activating STAT activation." (PMID 31754344, 2019). "IL11, PTPN6 and CISH were significantly associated with survival outcomes in patients from 9 cancer cohorts." (PMID 31684858, 2019). "Upon the formation of IL-11/IL-11R/GP130 hexameric complex, IL-11 mainly mediated cancer development through the induction and activation of the JAK/STAT3 signaling pathway." (PMID 30736824, 2019). "Stromal fibroblasts critically contribute to CRC tumorigenesis by producing hepatocyte growth factor (HGF) to establish the cancer stem cell phenotype and TGFβ treatment activates fibroblasts to enhance metastasis, partially via IL-11." (PMID 31028424, 2019).
cancer (continued). "The fact that the substantial loss of p-STAT3 is seen under conditions affecting only IL-6/IL-6R signaling suggests that the contribution of IL-11/IL-11R to maintaining constitutive p-STAT3 levels in these cancer cells is relatively small." (PMID 31491838, 2019). "Biomarkers IL-6 and IL-8, VEGF, MMP-9, MCP-1, IL-11, IGF-1, and Rantes are associated with different stages of cancer." (PMID 28763032, 2017). "Considerable evidence suggests that IL11 is also required for epithelial cell proliferation and survival, leading to the initiation and progression of cancer in the gastric mucosa and colon in humans and mice." (PMID 28186993, 2017). "We report that stromal LMO2 over-expression can stimulate secretion of interleukin-11 (IL-11) which facilitates proliferation and invasiveness of either prostate epithelial or cancer cells via IL-11 – IL-11 receptor α (IL11Rα) – STAT3 signaling pathway." (PMID 27028859, 2016). "Several antibodies specific to either IL-11 or its cognate receptors are reported with efficacy in mouse models of several cancers." (PMID 27916836, 2016). "Other studies have also shown that IL-11 stimulates inflammation, as well as cancer motility and invasion, through the JAK/STAT3, PI3K/Akt, and Ras/ERK pathways, ultimately resulting in an aggressive phenotype." (PMID 27487122, 2016). "Concurrently, miRNA regulation of the expression of interleukins (IL-11, IL-1β, IL-24 and IL-32) emerges as a useful tool in probing modulatory mechanisms of cancer promotion/suppression and their (in)direct implication in immunotherapeutic approaches." (PMID 25590298, 2015). "Collectively, miRNA regulation of the expression of interleukins (IL-11, IL-1β, IL-24 and IL-32) emerges as a useful tool in probing modulatory mechanisms of cancer promotion/suppression and their (in)direct implication in immunotherapeutic approaches." (PMID 25590298, 2015). "IL-11 is highly upregulated in many types of cancers and one of the most important cytokines during tumourigenesis and metastasis." (PMID 28781374, 2015). "Cancer cells have been shown to directly produce IL-11 and to stimulate osteoblasts to secrete IL-11, which in turn is known to suppress the activity of osteoblasts." (PMID 23311882, 2013). "KEGG pathway analysis revealed that the common genes expressed in FGF2 and IL-11 are enriched for cell adhesion, tight junction, insulin signaling and cancer pathways." (PMID 24194720, 2013). "IL-11 in turn increases osteolysis by stimulating osteoclast function, launching a vicious cycle of cancer growth and bone destruction." (PMID 22629385, 2012). "There was a sub-group of women with Grade 3 cancers that had very high levels of IL11 in the uterine flushings." (PMID 20553623, 2010). "IL11 levels in uterine flushings from women with Grade 1 cancers were higher than that of postmenopausal control women (p < 0.05)." (PMID 20553623, 2010). "Both IL11 and IL11Rα localized to vascular endothelial and smooth muscle cells while IL11 also localized to subsets of leucocytes in the cancer tissues." (PMID 20553623, 2010). "In agreement with our study, IL11 localised predominantly to cancer epithelial cells in a recent report." (PMID 20553623, 2010). "Positive immunostaining for IL11 was detected in all cancer tissues examined; meanwhile IL11Rα staining was present in all cancer tissues except two from grade 3." (PMID 20553623, 2010). "Our in vitro studies identified that IL11 (from 1 ng/ml) stimulated SOCS3 protein abundance in non-carcinoma HES cells." (PMID 20553623, 2010). "IL11 was present in uterine flushings and was significantly higher in women with Grade 1 carcinomas compared to postmenopausal women (p < 0.05)." (PMID 20553623, 2010). "Our results showed that NK cells expressed low levels of IL‐11R but had sufficient gp130, suggesting that cancer cells might inhibit NK cell proliferation through IL‐11 trans‐signaling." (PMID 41178513, 2026).
cancer (continued). "IL-11 is essential in the osteolytic cycle, interacting with cancer and bone cells." (PMID 40584290, 2025). "We also identify transcriptionally discrete iCAF phenotypes including a low activation/transition phenotype (IGF1+), likely the predominant iCAF in the current literature, as well as a more highly inflammatory IL11 + CAF subtype found within cancers of the GI tract." (PMID 39757146, 2025). "IL11 is an important contributor to cancer biology and may serve as a stromal cell-derived pleiotropic cytokine with profibrotic and cellular remodeling properties in disease progression." (PMID 41590789, 2025). "Label transfer using the HNSCC myeloid cells as a reference to identify myeloid phenotypes in CRC/ESCC scRNA-Seq datasets showed that IL11 + CAF similarly correlated with IL1B + inflammatory monocytes suggesting the same immunological niche is present in different cancer types." (PMID 39757146, 2025). "Mechanistic studies in mouse models and human cancer revealed that IL-11 production and phosphorylation of ERK are candidate targets of ω3FA, which could contribute to the reduction in inflammatory and CKD progression observed in clinical studies." (PMID 38732588, 2024). "TNF-α, IL-6, and IL-11 play a critical role in promoting the development and progression of cSCC by creating an inflammatory environment that supports the growth and survival of cancer." (PMID 40013270, 2024). "Whether anti-IL11 is effective in treating and/or preventing polyposis and/or cancers in PJS is currently under investigation." (PMID 38054591, 2023). "Additionally, in future studies, it would be interesting to explore the effect that enIL‐11 has in other cancer types and fibrotic diseases that have shown a dependence on IL‐11." (PMID 38023717, 2023). "IL-11 participates in the osteolytic cycle and interacts between cancer and bone cells." (PMID 37199584, 2023). "Furthermore, the PI3K/Akt pathway is activated by IL-11, particularly in cancer metastasis and tumorigenesis." (PMID 37199584, 2023). "However, we demonstrated that STAT1 is another downstream target of IL-11 in the regulation of cancer metastasis." (PMID 36593458, 2023). "Moreover, we identified that IL-11 derived from cancer cells at least partially inhibits the expression of GPR84 in OCPs by inactivating STAT1." (PMID 36593458, 2023). "Next, we investigated whether GPR84 can also be regulated by IL-11 in vivo during cancer bone metastasis." (PMID 36593458, 2023). "IL-11 was reported to be an important inflammatory cytokine for bone metastasis of cancer cells." (PMID 36593458, 2023). "IL11 can also drive cancer growth by promoting epithelial-mesenchymal transition (EMT)." (PMID 35883698, 2022). "Therapeutic strategies targeting the IL-11 signaling pathway induced by fibroblasts may be a promising clinical strategy for overcoming drug-resistant cancer." (PMID 35884907, 2022). "There is limited research into antibodies that target IL-11 or its receptor in cancers." (PMID 35053592, 2022). "Finally, these data suggest that cannabigerol and IFN-γ exert their anti-cancer properties via the inhibition of STAT3 (upregulated by IL-11 and LIF) and c-Jun/AP-1 (downregulated by Pentraxin2/SAP), respectively." (PMID 36923728, 2022). "In addition, the gut microbiota plays a critical role in the regulation of cancer metastasis through the IL11/circular RNA/miRNA/SOX9 axis." (PMID 36110534, 2022). "Aberrantly activated NRF2 in cancer cells may drive malignant progression and it has been reported that IL-11 is induced downstream of NRF2." (PMID 35163731, 2022). "IL-11 is secreted by cancer cells and TMA, i.e., cancer-associated fibroblasts and myeloid cells." (PMID 35884907, 2022). "For example, TGFβ derived from cancer cells enhances the secretion of IL-11 in CAFs." (PMID 36046433, 2021). "Therefore, the production of IL-11 by cancer cells within bone can be direct or indirect, and, in turn, IL-11 inhibits bone formation by suppressing osteoblast activity." (PMID 34201209, 2021).